APOA5 (apolipoprotein A5)
Diseases named in the same sentence as APOA5 in open-access papers (continued):
Sharing a sentence is not in itself a finding about the gene and the disease.
dyslipidemia (continued). "Among the DNA methylation patterns of APOA5 regions, exon 3 methylation showed a positively relation with TG concentration and with a lipoprotein profile associated with atherogenic dyslipidemia." (PMID 30053818, 2018). "Many genetic variants involved in the pathogenesis of the metabolic syndrome had been found to be associated with lipid metabolism, namely, SNPs in the APOA5, APOC3, and CETP genes." (PMID 29666642, 2018). "They genotyped APOA5 SNPs in 176 patients and 105 controls and the statistical analysis showed a significant association between -1131 T > C SNP with metabolic syndrome." (PMID 30053818, 2018). "A Japanese study examined 44 SNPs at 31 candidate genes and demonstrated that minor alleles at 2 of the APOA5 SNPs examined (c.3A > G and c.553G > T) were significantly associated with increased metabolic syndrome risk." (PMID 30053818, 2018). "Early in 2007, most studies about the physiological effects of APOA5 SNPs have focused on -1131 T > C and the results have already demonstrated an independent risk for -1131 T > C SNP in the development of metabolic syndrome." (PMID 30053818, 2018). "In this review, we focus on the association of gene and protein of apoA5 with obesity and metabolic syndrome, and provide new insights into the physiological role of apoA5 in humans, giving a potential therapeutic target for obesity and associated disorders." (PMID 30053818, 2018). "The most studied SNP located on the APOA5 promotor is probably 1131T>C (rs662799), in which the minor variant (C) has been associated with lower Apo-AV plasma concentration, which correlates with dyslipidemia." (PMID 30518135, 2018). "The statistical analysis showed a significant association between APOA5 -1131 T > C and APOA5 c.56C > G polymorphisms with metabolic syndrome in both Codominant and Dominant models." (PMID 25909077, 2015). "The effects of APOA5 polymorphisms and constructed haplotypes on metabolic syndrome were estimated using logistic regression analyses." (PMID 25909077, 2015). "Our results confirms the association of APOA5 -1131 T > C and c.56C > G variants with the predisposition to metabolic syndrome complications." (PMID 25909077, 2015). "The goal of the present study was to assess the relative contribution of SNPs in the APOA5 gene to the risk of metabolic syndrome and we studied the major APOA5 haplogroup profiles in MS patients in Moroccan Patients." (PMID 25909077, 2015). "In this case–control study we investigated the relative contribution of commons APOA5 polymorphisms and haplotypes to the risk of metabolic syndrome in Moroccan patients." (PMID 25909077, 2015). "The association of APOA5 polymorphisms with increased risk of metabolic syndrome was showed in several studies." (PMID 24684850, 2014). "Two polymorphisms of ApoA5, -1131T>C (rs662799) and c.56C>G (rs3135506) have been shown to be associated with TG level and dyslipidemia in different ethnics." (PMID 24708648, 2014). "These pleiotropic bivariate associations of APOA5 SNPs, in turn, affect the risk for metabolic syndrome (MS)." (PMID 24618354, 2014). "Our study confirms that ApoA5 gene polymorphisms, -1131T>C and c.56C>G are associated with the two criteria of Metabolic Syndrome, TG and WHR, respectively." (PMID 24708648, 2014). "Previous meta-analyses have reported that the APOA5 -1131T/C polymorphism is associated with an increased risk for developing metabolic syndrome." (PMID 24586566, 2014). "In conclusion, rs964184 in the APOA5 region is associated with elevated TG plasma levels and presence of the metabolic syndrome in patients with clinically manifest vascular disease." (PMID 24979386, 2014). "We assessed the associations between the APOA5 −1131T>C polymorphism and lipid parameters and other risk factors of the metabolic syndrome in Korean subjects." (PMID 23509746, 2013).
dyslipidemia (continued). "First, although we only explored the effect of APOA5 −1131T>C variant on plasma lipid levels and the prevalence of metabolic syndrome, there are still many other APOA5 SNPs, gene-gene and/or gene-environment interactive factors needed to be considered." (PMID 23468858, 2013). "In the current study, we demonstrated that the APOA5 −1131T>C polymorphism is associated with the metabolic syndrome because of its remarkable effect on serum triglyceride levels in Korean subjects." (PMID 23509746, 2013). "The reduced risk of metabolic syndrome observed in carriers of APOA5 -12,238C and APOA4 Ser347 alleles merely reflected the negative linkage disequilibrium existing between these alleles and the APOA5 Trp19 allele." (PMID 18789138, 2008). "The APOA5 Trp19 allele increased the odds ratio for metabolic syndrome, whereas the APOA5 -12,238C and APOA4 Ser347 alleles decreased it." (PMID 18789138, 2008). "The goal of the present study was to assess the contribution of SNPs in the APOA5/A4/C3/A1 cluster to the risk of metabolic syndrome." (PMID 18789138, 2008). "The GTACC haplotype (carrying the APOA5 Trp19 allele on the common background) was associated with a 33% greater risk of metabolic syndrome (p < 0.005)." (PMID 18789138, 2008). "The goal of the present study was to assess the effect of genetic variability at the APOA5/A4/C3/A1 cluster locus on the risk of metabolic syndrome." (PMID 18789138, 2008). "Since the APOC3 and APOA5 SNPs are in different haplotype blocks, the association with metabolic syndrome was tested for the two blocks independently." (PMID 18789138, 2008). "The APOA5 Trp19 allele increased susceptibility to metabolic syndrome via its impact on plasma triglyceride levels." (PMID 18789138, 2008). "Furthermore, this allelic variant of the APOA5 gene has been linked to an increased susceptibility to dyslipidemia." (PMID 40428368, 2025). "On the other hand, in recent years, apolipoprotein A5 (ApoA5), a newly discovered member of the apolipoprotein superfamily, has been closely associated with obesity and the development of metabolic syndrome and has a significant impact on regulating triglyceride metabolism." (PMID 39280566, 2024). "Interestingly, a single nucleotide polymorphism (SNP) in APOA5 was associated with dyslipidemia only in male subjects." (PMID 37892463, 2023). "A study conducted in Spain showed that single nucleotide polymorphisms (SNPs) in genes associated with atherogenic dyslipidemia, particularly the variants rs3135506 and rs662799 of the apolipoprotein-A5 (APOA5) gene, can influence the CD4 T-cell levels in chronic HIV-infected patients." (PMID 35628408, 2022). "The serum ApoA5 level of the patients enrolled in this study was detected to investigate whether there is an association between the serum ApoA5 level, metabolic syndrome, and NAFLD in the general population of China." (PMID 35854768, 2022). "Moreover, several studies in different ethnic groups have reported a strong association between APOA5 -1131T/C polymorphism and the development of metabolic syndrome." (PMID 35886029, 2022). "In addition to rs9804646, the SNP rs651821 in the female cohort was also present in APOA5 and was confirmed to have a significant association with dyslipidemia in the Korean population." (PMID 36419087, 2022). "In addition to the well characterized common APOA5 variants, rare variants in the APOA5 gene have been documented and implicated in the development of dyslipidemia and associated diseases." (PMID 29686695, 2018). "Several studies have given evidence for the interaction between APOA5 SNPs and increased risk of obesity and metabolic syndromes, suggesting that the genetic variability of APOA5 plays an important role in modulating lipid metabolism, and the mechanisms of action seems to be clear." (PMID 30053818, 2018). "Indeed, APOA5 SNPs were reported to be associated with two components of metabolic syndromes: higher TG levels and lower HDL levels." (PMID 30053818, 2018).
dyslipidemia (continued). "However, recent advances in genome-wide association studies (GWAS) have provided a fairly good view of the contribution of APOA5 variants to dyslipidemia in several populations." (PMID 29686695, 2018). "Furthermore, in 2011, a more comprehensive study was conducted by Ong, in terms of both gene coverage and sample size to investigate the associations of APOA5 gene SNPs with the metabolic syndrome in the Hong Kong and Guangzhou Chinese." (PMID 30053818, 2018). "Furthermore, the variants of APOA5 gene in human of different ethnic groups not only influence plasma TG concentration but also have an association with the prevalence of obesity or metabolic syndrome." (PMID 30053818, 2018). "In this review, we focus on the association of APOA5 gene polymorphisms with obesity and the metabolic syndrome, and the potential mechanisms by which apoA5 may contribute to individual susceptibility to these conditions." (PMID 30053818, 2018). "Similar to what is observed in obese individuals by Turnbaugh's group, a lower level of diversity of gut microbes was present in individuals with metabolic syndrome; and some of the taxa associated with metabolic syndrome are linked to a genetic variant in the apolipoprotein A5 gene (APOA5)." (PMID 28713266, 2017). "Third, genetic factors, especially the genes involved in obesity and lipid metabolism, such as PPAR and APOA5 genetic polymorphism, should be taken into consideration, because prior studies demonstrated that Europeans had higher incidence of metabolic syndrome associated with lipid metabolism." (PMID 26907312, 2016). "In summary, variants that are strongly linked to known forms of dyslipidemia (in APOA5 and APOE), could at most explain only 7 (3.0%) of all 234 affected FCH individuals, thus being of minor importance in our FCH family sample." (PMID 27227539, 2016). "Taking these findings into consideration, we speculate that the synergistic effect of obesity and dyslipidemia caused by APOA5 polymorphisms may confer the increased risk of CKD." (PMID 25311932, 2014). "Therefore, APOA5 variant was a significant predictor for high triglyceride risk and the APOA5 haplotypes affected dyslipidemia appreciably among the Moroccan population." (PMID 24684850, 2014). "APOA5 SNPs have also been associated with metabolic syndrome (MS)." (PMID 24618354, 2014). "In order to systematically evaluate the associations between APOA5 gene −1131T>C polymorphism and fasting lipid parameters and the risk of metabolic syndrome, we conducted a case-control study in a Chinese population and a meta-analysis based on currently reported studies." (PMID 23468858, 2013). "The results of the present study further suggest that the association of SNPs in this cluster with metabolic syndrome may be explained by the propensity of plasma triglycerides to increase in APOA5 Trp19 allele carriers." (PMID 18789138, 2008). "The decreased risk of metabolic syndrome observed in APOA5 -12,238C and APOA4 Ser347 carriers merely reflected the fact that the APOA5 Trp19 allele was in negative linkage disequilibrium with the common alleles of APOA5 -12,238T>C and APOA4 Thr347Ser polymorphisms." (PMID 18789138, 2008). "Compared with homozygotes for the common allele, the odds ratio (OR) [95% CI] for metabolic syndrome was 1.30 [1.03–1.66] (p = 0.03) for APOA5 Trp19 carriers, 0.81 [0.69–0.95] (p = 0.01) for APOA5 -12,238C carriers and 0.84 [0.70–0.99] (p = 0.04) for APOA4 Ser347 carriers." (PMID 18789138, 2008).
dyslipidemia (continued). "Our results showed that the APOA5 Trp19 allele was associated with an increased risk of metabolic syndrome and that this association could possibly be explained by an increase in plasma triglyceride levels." (PMID 18789138, 2008). "The goal of the present study was to assess the relative contribution of SNPs in the APOA5/A4/C3/A1 locus to the risk of metabolic syndrome by analyzing a limited number of representative SNPs within the cluster and a large population-based sample from 3 areas of France." (PMID 18789138, 2008). "The APOA5 Trp19 allele conferred an increased risk of metabolic syndrome (p = 0.03)." (PMID 18789138, 2008). "Other studies have reported associations between APOA5 SNPs and metabolic syndrome." (PMID 18789138, 2008). "The HDL is another component of metabolic syndrome that might be affected by ApoA5 loss." (PMID 38867151, 2024). "While the apolipoprotein 5 (APOA5) gene is considered integral to lipid homeostasis, two different polymorphisms of this gene, rs662799 A > G and rs651821 T > C, were associated with a significant increase in the incidence of dyslipidemia in male and female subjects, respectively." (PMID 37892463, 2023). "Moreover, rs651821 of the APOA5 gene was also shown to be associated with dyslipidemia." (PMID 36419087, 2022). "Replicating our findings in larger Moroccan cohorts from different ethnic groups and geographic regions, could overcome these limitations and provide sufficient statistical power to reach clear conclusion on the role of APOA5 polymorphisms in metabolic syndrome susceptibility." (PMID 25909077, 2015). "Indeed, other studies have reported associations between APOA5 SNPs and metabolic syndrome." (PMID 18789138, 2008). "This work highlights APOA5′s critical role in the obesity-sensitive regulation of lipid metabolism and its contribution to dyslipidemia’s heritability." (PMID 40428368, 2025). "Another SNP of APOA5, rs9804646, which is located at 11q23.3, was found to be a dyslipidemia-related SNP in both the male and female cohorts." (PMID 36419087, 2022). "Of note, the other two SNPs, rs56156922 (CETP) and rs662799 (APOA5), appeared to be dyslipidemia-related SNPs found only in men." (PMID 36419087, 2022). "Exome-wide association studies (EWASs) identified eight SNPs related to the dyslipidemia-dominant subtype with genome-wide significance, which were located in the genes APOA5, BUD13, ZNF259, and WNT4." (PMID 36551856, 2022). "Moreover, single-nucleotide variants (SNVs) in the APOA5 gene, such as rs651821 and rs3135506, have been associated with metabolic syndrome and its traits,; recently, the involvement of rs662799 (−1131T > C) in lipid profile and metabolic syndrome has been shown too." (PMID 35745158, 2022). "Subsequently, we further analyzed the relationship between the different components of the metabolic syndrome and the levels of ApoA5." (PMID 35854768, 2022). "Of great interest is also the recent identification of the relative APOA5 protein as a major regulator of triglyceride storage in hepatocyte intracellular lipid droplets, suggesting for this gene a role in obesity and metabolic syndromes." (PMID 33673460, 2021). "Variants in APOA5 are associated with triglyceride levels, diseases involving lipid traits, CAD, total cholesterol levels, and metabolic syndrome." (PMID 33763119, 2021). "Generally, SNPs of APOA5 are associated with dyslipidemia, which is a component of MetS." (PMID 26365620, 2015). "Moreover, only four SNPs in APOA5 gene were investigated in this study, we cannot exclude the possibility that other SNPs or particular haplotypes may have a significant impact on genetic susceptibility to metabolic syndrome." (PMID 25909077, 2015).
dyslipidemia (continued). "The apolipoprotein A5 (APOA5) gene −1131T>C (rs662799) has been suggested to be involved in the pathway of lipid homeostasis and the development of metabolic syndrome (MetS)." (PMID 23468858, 2013). "Overall, this suggests that APOA5 and APOA4 genetic variability affected susceptibility to metabolic syndrome." (PMID 18789138, 2008). "Given its role in triglyceride metabolism and its interaction with insulin, the APOA5 gene is a candidate gene for metabolic syndrome." (PMID 18789138, 2008). "In contrast, the APOA5 -12,238C (p = 0.01) and the APOA4 Ser347 (p = 0.04) alleles were associated with a lower risk of metabolic syndrome." (PMID 18789138, 2008). "The other haplotype (CCTTC, carrying the APOA5 12,238C, the APOA4 Ser347 and the APOC3 -482T alleles) was associated with a 26% reduction in metabolic syndrome risk (p = 0.03)." (PMID 18789138, 2008). "APOA5 (p = 3.45 × 10−8, FDR = 6.31 × 10−4) and ZPR1 (p = 1.80 × 10−6, FDR = 0.016) were associated with SGA-induced TG changes; these genes were related to TG, HDL, and LDL levels and metabolic syndrome." (PMID 40830362, 2025). "Also, rs180365 (LINC02702‐BUD13), rs964184 (ZPR1), rs662799 (ZPR1), rs10750097 (novel APOA5), rs6589574 (APOA1), rs562179 (novel SIK3), associated with lipid‐related traits and/or metabolic syndrome, showed evidence of interaction with TSS of APOA1." (PMID 40665476, 2025). "Genome-wide association studies (GWAS) have identified several candidate genes, including apolipoprotein A5 (APOA5), which may influence susceptibility to metabolic syndrome (MetS) and its components." (PMID 38867151, 2024). "APOA5 was used as a biomarker for sepsis-induced dyslipidemia." (PMID 36755189, 2023). "Additionally, rs9804646 in the APOA5 gene, as well as rs56156922 and rs429358 in the APOE gene, were associated with dyslipidemia." (PMID 36419087, 2022). "Interestingly, rs662799 of APOA5 also appeared as a dyslipidemia-related SNP only in the male cohort, indicating that there are sex-related differences in the prevalence of dyslipidemia." (PMID 36419087, 2022). "Studies have also reported that ApoA5 is closely related with obesity, dyslipidemia, insulin resistance and metabolic syndrome, and it is expected that ApoA5 can promotes hepatic TG storage and contribute the pathogenesis of non-alcoholic fatty liver disease (NAFLD)." (PMID 31077206, 2019). "Obesity has been identified to promote the development of metabolic syndrome, so we could speculate APOA5 SNPs may also have potential impact on the metabolic syndrome." (PMID 30053818, 2018). "Moreover, the apolipoprotein A5 haplotypes, including rs6589566, were implicated in the elevation of the TG/HDL-c ratio and the risk for metabolic syndrome in a Korean population." (PMID 29410832, 2018). "As a novel regulator of lipid storage in adipocytes, apoA5 may serve an important role in whole body energy homeostasis and may be a potential therapeutic target for the treatment of obesity and metabolic syndromes." (PMID 30053818, 2018). "From this point, since fibrates could specifically activate PPAR-α, the mechanism of fibrates in lowering TG and inhibiting dyslipidemia could be explained, at least partly, by up-regulating APOA5 expression." (PMID 30053818, 2018).